NLRP3 (NLR family pyrin domain containing 3)
Diseases named in the same sentence as NLRP3 in open-access papers (continued):
Sharing a sentence is not in itself a finding about the gene and the disease.
depression (continued). "Furthermore, Kaempferol-3-O-sophoroside not only improves depression-like behavior in mice but also promotes BDNF production in the hippocampus and induces autophagy to reduce NLRP3-mediated neuroinflammation." (PMID 40936908, 2025). "More importantly, the present study discovered that KF1 could reverse the pathological changes in the LPS-induced depression model by activating PPAR-γ/CX3CR1/Nrf2 signaling, and suppressing NF-κB/NLRP3 signaling pathways." (PMID 40308754, 2025). "Cytokines such as PGC-1α, NLRP3, and BDNF can influence mitochondrial energy metabolism by regulating mitochondrial biogenesis, immune inflammation, and neuroplasticity, thereby mediating the occurrence and progression of depression." (PMID 40699781, 2025). "Notably, our observations suggest a significant influence of VTX on this specific molecular pathway, aligning with other studies that show certain antidepressants affecting NLRP3 and ASC expression across the hippocampus to improve depression-like behaviors." (PMID 39005130, 2025). "In addition, baicalin can inhibit the activation of the glycogen synthase kinase-3 beta (GSK3β)/NF-κB/NLRP3 pathway, promoting neuronal maturation and protecting against neuronal damage, thereby alleviating CUMS-induced depression-like behavior." (PMID 40936908, 2025). "The positive drug fluoxetine could also decrease NLRP3 and mature IL-1β levels, suggesting the inhibitory activity of neuroinflammation by PSP in CRS-induced depression." (PMID 39204578, 2024). "Besides, LPS interfered mitochondrial function and mitophagy via activating NLRP3 inflammasomes in N9 microglia and hippocampus of db/db mice, but exendin-4, a GLP-1R activator, alleviated above changes and relieved depression-like behaviors in diabetic mice." (PMID 37548945, 2024). "We have observed a significant amelioration in depression‐like behavior upon SBP administration during the treatment of AMI, suggesting that this effect may be attributed to the inhibition of NLRP3‐mediated pyroptosis." (PMID 38970230, 2024). "The promotion of NLRP3 inflammatory corpuscles will activate GSDMD-N, which will lead to pyroptosis, indicating that inhibiting pyroptosis is an effective treatment strategy to prevent depression." (PMID 39684254, 2024). "In this study, NLRP3 inflammasome was activated in atria in both LPS- and CUS-induced depression." (PMID 38261756, 2024). "In addition, the expression levels of TLR4, P65, P-P65, NLRP3, ASC, caspase-1, and IL-1β were elevated in depression models." (PMID 38261756, 2024). "In conclusion, we investigated the impact of SBP treatment on depressive‐like behavior in rats with depression following AMI, potentially achieved through amelioration of neuroinflammation and microglial pyroptosis mediated, at least partially, by the NLRP3/Caspase‐1/GSDMD signaling pathway." (PMID 38970230, 2024). "Currently, the regulatory relationship between CGAS-STing-NLRP3 signaling axis and depression has not been clarified." (PMID 38643466, 2024). "Recent investigations have underscored that hyperglycemia stimulates inflammatory factors to activate microglial NLRP3 in hippocamp, upregulating P2X7R and enhancing ROS production and TXNIP expression, all of which likely mediate the emergence of depression in diabetic mice model." (PMID 38916735, 2024). "NLRP3 function can also be modulated through the inhibition of CYP17A1 and CYP19A1 via clotrimazole (30 mg/kg/day), which produces an anti-inflammatory response and reduces depression-like behaviors." (PMID 38791125, 2024). "Regarding the statistically significant correlation between HDRS and measured parameters, reducing HDRS and relieving depression symptoms might lead to a reduction in IL-6, STAT3, NLRP3, and an elevation in AMPK." (PMID 38855751, 2024). "In addition to suppressing HIF-1α/NLRP3 inflammatory signaling, SGB significantly attenuated thalamic hemorrhage-induced CPSP and comorbid anxiety and depression." (PMID 36944982, 2023).
depression (continued). "Intriguingly, SIRT1 inhibitor countervailed the inhibitory effect of AG on NLRP3 inflammasome, which indicated that targeting the SIRT1-mediated NLRP3 inflammasome axis might be a possible mechanism of AG to treat depression." (PMID 37920216, 2023). "In addition to the myriad of new therapeutic agents developed to target NLRP3, fluoxetine (FLX), an FDA-approved drug for treating clinical depression, has been recently identified to bind and inhibit NLRP3." (PMID 37242422, 2023). "Numerous studies have found that inhibiting the expression of NLRP3 inflammasome can significantly improve depressive-like behaviors in mice, but the research on its effect on cognitive decline in depression and its mechanism is still lacking." (PMID 37165444, 2023). "A few studies reported that NLRP3 protein levels are increased in the peripheral blood mononuclear cells of patients with depression compared to non-depressed subjects." (PMID 37763063, 2023). "NLRP3-dependent pyroptosis and endothelial dysfunction might be common mechanisms for CVD and depression comorbidity." (PMID 37763063, 2023). "The NLRP3 inflammasome complex, which is considered a possible common mechanism in the presence of systemic diseases and comorbid depression, has not been previously evaluated in a clinical sample examining the association of AMI and depression." (PMID 37763063, 2023). "The NLRP3 inflammasome, which is a key component of the NLR family that triggers the innate immune response, has been reported to be involved in the pathophysiology and treatment of depression." (PMID 36909192, 2023). "SGB inhibited HIF-1α/NLRP3 inflammatory signaling and could treat CPSP and comorbid anxiety and depression." (PMID 36944982, 2023). "However, pharmacological activation of thalamic HIF-1α/NLRP3 signaling eliminated the therapeutic effect of SGB on CPSP with comorbid anxiety and depression." (PMID 36944982, 2023). "This study demonstrated for the first time that SGB could improve CPSP with comorbid anxiety and depression by increasing cerebral blood flow and inhibiting HIF-1α/NLRP3 inflammatory signaling." (PMID 36944982, 2023). "Upregulated HIF-1α/NLRP3 signaling in the peri-thalamic sites activated microglia and astrocytes, releasing pro-inflammatory cytokines and oxidative stress, leading to CPSP and comorbid anxiety and depression." (PMID 36944982, 2023). "Fluoxetine (FLX), an FDA-approved drug for clinical depression, has been recently identified to possess anti-NLRP3 activity, in contrast to several other antidepressants that do not block NLRP3." (PMID 37242422, 2023). "Clinical evidence has demonstrated significantly higher concentrations of inflammatory cytokines, such as IL-1β, IL-6 and TNF-α activated by NLRP3 in the cerebrospinal fluid and serum of patients with depression compared to non-depressed individuals." (PMID 37474898, 2023). "However, pharmacological activation of thalamic HIF-1α and NLRP3 with specific agonists significantly eliminated the therapeutic effects of SGB on mechanical allodynia and anxiety- and depression-like behaviors following thalamic hemorrhage." (PMID 36944982, 2023). "Altogether, these findings reveal that modulating the HO-1/MAPK, P13K/Akt, SIRT1- NLRP3, and Notch/HES-1-NF-κB signaling pathways might be the mechanism of AG in mitigating neuroinflammation, cognitive impairment, depression, and AD." (PMID 37920216, 2023). "Three different NLRP3 inflammasome genes (NLRP3, ASC, and Caspase-1) were found to be substantially upregulated at the mRNA level following LPS treatment relative to baseline, consistent with a central role for this pathway in LPS-induced depression." (PMID 35113011, 2022). "Only one report shows that NLRP3 protein levels are increased in the peripheral blood mononuclear cells of patients with depression compared to non-depressed subjects." (PMID 35295780, 2022).
depression (continued). "In addition, the licorice-derived flavonoid isoliquiritin was shown to suppress NLRP3-mediated pyroptosis via the miRNA-27a/SYK/NF-kB axis in both the LPS and the chronic social defeat stress models of depression." (PMID 36613574, 2022). "In the chronic unpredictable mild stress (CUMS) mouse model, human umbilical cord mesenchymal stromal cells reduced neuronal complement C3 receptors and thereby attenuated NLRP3 activation-induced neuroinflammation and ultimately ameliorated CUMS-induced depression-like behavior." (PMID 35722622, 2022). "First, current studies on pyroptosis and neurological diseases are limited to NLRP3 and AIM2 inflammasomes, and the link between other types of pyroptosis-related inflammasomes, such as NLRC4, NLRP6, and depression, needs to be further investigated and elucidated." (PMID 35722622, 2022). "Of note, in the LPS-induced depression mouse model, the TRPV4 inhibitor HC067047 or TRPV4 shRNA could effectively rescue the abnormal behaviors by decreasing the expression of the NLRP3." (PMID 36552524, 2022). "The direct pathogenesis of depression remains unclear, and some studies now suggest a close relationship between MDD and neuroinflammation triggered by NLRP3 inflammasomes." (PMID 35937897, 2022). "The present study supports the role of MG to modulate NLRP3, NLRC4, and AIM2 inflammasome activation, both in primary cortical microglia and in a mouse model of anxiety and depression, as a potential therapeutic approach to addressing immune-inflammatory-based disorders." (PMID 35740286, 2022). "The mechanism of baicalin against CMS-induced depression was partially achieved by increasing levels of DCX, neuron-specific enolase (NSE), and BDNF, reducing oxidative stress, and modulating the GSK3/NF-κB/NLRP3 signal cascade in the HIP." (PMID 35668399, 2022). "Liquiritin attenuates depression-like behavior of CUMS mice and inhibited cytokines levels triggered by NLRP3 inflammasome, suggesting the antidepressant action is, at least partially, associated with antioxidant stress and inhibition of NLRP3 inflammasome activation." (PMID 35069768, 2022). "However, the relationship between NLRP3 inflammasome activity, BHB, and depression‐related behavior is yet to be established, and understanding its pathophysiology is of great interest." (PMID 33609086, 2021). "Taken together, these findings suggested that Cy has therapeutic potential for treating depression and that this antidepressant effect may be attributed to SIRT3 stimulated neuroplasticity enhancement by suppressing NLRP3 inflammasome." (PMID 33132912, 2020). "Studies show that the NLRP3 inflammasome in blood cells of patients with MDD was activated, and the increased serum levels of IL-1β and IL-18 were positively correlated with Beck Depression Inventory (BDI) scores." (PMID 31814820, 2019). "Activated NLRP3 has been found in MDD patients and animal models of depression." (PMID 31053149, 2019). "In summary, exercise regulates signaling pathways such as NF-κB, NLRP3, UCP2, and cGAS-STING, reduces the release of mtDNA and pro-inflammatory factors, inhibits the inflammatory response, and decreases ROS production, thereby improving mitochondrial function and alleviating depression." (PMID 40699781, 2025). "However, when the hyperpolarization-activated cyclic nucleotide-gated cation channel 1(HCN1) was knocked out by injecting a virus into the hippocampus, the expression of NLRP3 inflammasome-related proteins in PSD mice decreased, and both anxiety- and depression-like behaviors were alleviated." (PMID 40936908, 2025). "In addition, we only detected peripheral RvD1, NLRP3, and several common cytokines, without exploring other cytokines which have been reported to participate in the development of depression." (PMID 38627683, 2024).
depression (continued). "Inflammation plays a pivotal role in depression, evidenced by heightened levels of inflammatory cytokines and the activation of the nucleotide oligomerization domain (NOD)-like receptor family, pyrin domain-containing protein 3 (NLRP3) inflammasome in patients and animal models." (PMID 39337263, 2024). "However, whether gene expression of NLRP3 is still activated in the peripheral blood of adolescent patients with MDD, like adult depression, is still unclear." (PMID 38627683, 2024). "Our results suggested that chronic stress induced microglial pro-inflammatory activation, cGAS–IFI16–STING activation, NF-κB signaling pathway priming, as well as NLRP3 inflammasome activation in BLA, and that were associated with negative emotional behaviors, including anxiety and depression." (PMID 36793064, 2023). "This study aimed to assess the possible role of the NOD-like receptor protein 3 (NLRP3) inflammasome pathway and the high-sensitivity C-reactive protein (hsCRP) in patients with incident myocardial infarction in the presence or absence of depression." (PMID 37763063, 2023). "For example, activated NLRP3 inflammasome by microbiota affects the acute pancreatitis, and the expression of NLRP3 also shapes the composition of the intestinal flora, but the detailed understanding of their interactions in depression is lacking." (PMID 37293210, 2023). "NLRP3 activation has been hypothesized to bridge CVD and depression." (PMID 37763063, 2023). "We carried out an anti-depression experiment in vivo to identify how TTWC can improve depression-like behavior and alleviate neuronal damage in the hippocampus and prefrontal cortex by regulating the levels of neurotransmitters, the HPA axis, and the NLRP3 signaling pathway." (PMID 35237160, 2022). "However, to our knowledge, the NLRP3 inflammasome has not been reported to be involved in the pathological process of anxiety and depression in AD." (PMID 36267291, 2022). "However, no clear correlation was found between the active NLRP3 levels in the prefrontal cortex and SD‐induced depression‐ and anxiety‐like behaviors." (PMID 33609086, 2021). "NLRP3 inflammasome mediates the pathogenesis of depression via neuroinflammation, but it is not clear whether and how NLRP3 inflammasome is involved in the molecular mechanism of depression." (PMID 35096901, 2021). "Unlike NLRP3, NLRP1 is mainly presented in neurons and dominantly implicated in neuronal injury pathologies and cognitive impairment, which is a core feature of subjects with depression." (PMID 32513185, 2020). "Since astrocyte dysfunction was found to be involved in depression and antibiotic cocktail treatment did not influence on astrocyte activation, we next examined the effect of transplantation of the gut microbiota from NLRP3 KO mice on astrocyte function." (PMID 31439031, 2019). "The present results might also reflect greater activation of the NLRP3 inflammasome in peripheral blood mononuclear cells from subjects with depression, as suggested in a recent study of depressed and nondepressed medically healthy subjects." (PMID 25054133, 2014). "Our study, the first of its kind exploring VTX potential in modulating the NLRP3 inflammasome in a time- and area-specific manner in the brain, could serve as a starting point for further investigations into VTX molecular mechanisms in treating depression and cognitive impairments." (PMID 39005130, 2025). "The activation of the NLRP3 inflammasome may induce inflammation, enhance BBB permeability, exacerbate recurrent stroke, and the activation of hippocampal microglial NLRP3 inflammasome vesicles can facilitate chronic stress-induced depression-like behavior in rats." (PMID 40458804, 2025).
depression (continued). "In conclusion, our study, the first of its kind exploring VTX potential in modulating the NLRP3 inflammasome in a time- and area-specific manner in the brain, could serve as a starting point for further investigations into VTX molecular mechanisms in treating depression and cognitive impairments." (PMID 39005130, 2025). "A recent study found that the NLRP3 level in subjects with “reactive” depression (occurring as the result of a stressor) was significantly lower than that of those subjects diagnosed with “endogenous” depression (occurring in the absence of stress) and in healthy controls." (PMID 37763063, 2023). "In the chronic unpredictable mild stress (CUMS)-induced depression mouse model, researchers found significantly elevated levels of IL-1β protein in serum and hippocampus, but not in NLRP3 knockout mice, probably because NLRP3 knockout inhibited MAPK pathway and NF-κB pathway activation." (PMID 35937897, 2022). "To explore the effects of depression on the activation of NLRP3 inflammasome in patients with AIH, we collected liver tissues from AIH patients with depression, AIH patients without depression, and age‐ and sex‐matched controls." (PMID 41503678, 2026). "The mRNA expression levels of NLRP3, CASP1, and IL1B were higher in liver biopsies from AIH patients with depression than in those without depression." (PMID 41503678, 2026). "The NLRP3 inflammasome is the most widely studied in noninfectious diseases, and its abnormal activation is closely related to the pathogenesis of both CVD and depression." (PMID 41194915, 2025). "In addition to depression, the role of PM2.5 induced NLRP3-mediated pyroptosis in Alzheimer's disease should not be underestimated." (PMID 33456360, 2021).